TNF (tumor necrosis factor)
Diseases named in the same sentence as TNF in open-access papers (continued):
Sharing a sentence is not in itself a finding about the gene and the disease.
Arthritis (continued). "In the present study we demonstrate that HMGB1-triggered joint inflammation is not mediated via the TNF pathway since the arthritis incidence and severity remained similar in mice deficient for TNFα and in backcrossed C57Bl6 control animals." (PMID 18582368, 2008). "IL-15 produces a number of effects which may be relevant to the pathogenesis of arthritis including recruitment and activation of T lymphocytes into the synovial membrane and induction of TNFα production." (PMID 18234077, 2008). "Inhibition of TNFα, IL-1β, and IL-6 production is beneficial in several inflammatory diseases including arthritis and numerous efforts have been devoted in the design of novel therapies aimed at blocking the production and/or the biological effects of these important pro-inflammatory cytokines." (PMID 18493620, 2008). "Decreased SDF-1 production by bone marrow stromal cells in response to TNF overexpression may therefore be one of the mechanisms mediating release of OCPs to the peripheral blood in mice with TNF-induced arthritis or in patients with inflammatory arthritis." (PMID 18371213, 2008). "Another possibility to explain the lack of correlation between the clinical course and HMGB1 expression following infliximab treatment could be that HMGB1 may be more dependent on the IL-1 pathway than the TNF pathway in the pathogenesis of arthritis." (PMID 18346273, 2008). "Our observation that RP105-deficient mice developed severe arthritis in response to anti-CII antibody and LPS and produced more TNF-α in response to LPS indicated that the hyporesponsiveness of RP105-/- B cells might be overcome by other cells in vivo." (PMID 18847495, 2008). "We hypothesise that autoantibodies targeting citrullinated fibrinogen could result in IC-mediated arthritis based on mechanisms analogous to those observed in the K/BxN model and via macrophage FcγRIIa-mediated TNF production." (PMID 18710572, 2008). "The role of endogenous TNFα in the induction and propagation of arthritis is well established." (PMID 18380898, 2008). "Previous studies demonstrated an increase in circulating OCPs in patients and animals with arthritis and that OCP frequency is reduced in response to anti-TNF therapy, suggesting that OCPs may play important roles in the pathogenesis of arthritis." (PMID 17997858, 2007). "We used TNF-transgenic (Tg) mice and mice with serum-induced arthritis." (PMID 17997858, 2007). "Cachexia caused by arthritis, cancer and AIDS have all been correlated with elevated TNFα levels." (PMID 18070349, 2007). "In addition, endostatin overexpression inhibited development of arthritis in the joints of TNF-transgenic mice." (PMID 16839420, 2006). "Moreover, TNFα inhibition decreases the severity of arthritis, and both monoclonal antibodies to TNFα and a soluble tumor necrosis factor receptor analog have been used as effective therapies for RA and for other types of inflammatory arthritis." (PMID 17078892, 2006). "In addition, the transfer of hIL-32β-producing CD4+ T cells significantly exacerbated collagen-induced arthritis, and a TNFα blockade cancelled the exacerbating effects of hIL-32β." (PMID 17078892, 2006). "In collagen-induced arthritis, IL-18 promotes arthritis via tumor necrosis factor-alpha induction." (PMID 16563174, 2006). "TNF blockade was initiated at the stage of early arthritis and was continued for six weeks." (PMID 16507121, 2006). "Furthermore, hIL-32β-transduced CD4+ T cells showed marked exacerbation of collagen-induced arthritis, an effect that was, in part, cancelled by TNFα blockade." (PMID 17078892, 2006). "We found that the combination of low dose anti-TNFα associated with mucosal tolerization to the arthritogenic T cell epitope led to a significant reduction of arthritis clinically as well as histologically, to a degree entirely comparable with what was achieved with full dose anti-TNFα." (PMID 17183718, 2006).
Arthritis (continued). "BZXD can reduce IL-1β level and relieve the arthritis which might result from regulating the immunity function, suppressing the TNF-α expression or combining with the TNF-α receptor and then interrupt the cytokine net." (PMID 23674954, 2005). "Moreover, studies involving LPS-induced macrophages and adjuvant-induced arthritis in rats demonstrate that the production of pro-inflammatory cytokines such as IL-6, IL-1β, and TNF-α requires activation through the NF-κB, JAK1-STAT1/3, and MAPK signaling pathways to exert inflammatory effects." (PMID 40170729, 2025). "Thus, the interplay between arthritis and inflammatory atherosclerosis, as well as the effects of anti-TNF biologics on these pathologies, might independently involve nAAbs." (PMID 38542402, 2024). "For instance, Wistar rats with arthritis that received oral treatments of hesperidin (50 mg/kg) and daidzein (20 mg/kg) (both phenolic compounds) for 21 days showed a significant reduction in TNF-α (tumor necrosis factor-alpha) levels, a key cytokine in chronic inflammation." (PMID 39598361, 2024). "Importantly, post adjuvant injection, levels of TNF-α were also significantly higher in the arthritis control group compared with the normal control group (15.6 ± 3.7 pg/L and 156.6 ± 41.3 pg/L, respectively) (p < 0.001), confirming successful induction of the inflammatory response." (PMID 39687160, 2024). "In addition, a recent study indicated that blocking TLR4 could effectively attenuate monoiodoacetate-induced arthritis in rats by relieving joint pain and reducing the expression of TNF-α, IL-1β, and matrix metallopeptidase-13 (MMP13)." (PMID 36785752, 2023). "Therefore, although tea and tea polyphenols can neutralize the inflammatory effects of IL-1β and IL-6, they also effectively utilize TNF-α to play its basic function of regulating the uncontrolled proliferation of activated synovial fibroblasts to improve the functional status of arthritis joints." (PMID 37033930, 2023). "Once treated with anti-TNF-α antibodies, Cry1−/−Cry2−/− mice progression of arthritis was halted, suggesting that the circadian rhythm and arthritis affect each other, and disruptions in the circadian rhythm mouse clock genes Cry1 and Cry2 may hasten the progression of inflammatory arthritis." (PMID 37378201, 2023). "Receptor activator of nuclear factor-κB ligand (RANKL) is a member of the tumor necrosis factor (TNF) superfamily and constitutes a key regulator in osteoclast development, inducing physiological and pathological bone resorption in osteolytic diseases, such as osteoporosis and arthritis." (PMID 37568820, 2023). "Similarly, the evaluation of TNF-Tg mice with severe arthritis may have reached a ceiling of disease activity where the relationship with αSMA+ PLV-LMC coverage was unable to be adequately assessed." (PMID 35882971, 2022). "Thus, PAD2 may be important in the innate immune cells thought to be the predominant drivers of TNF-induced arthritis, with a less critical role in the adaptive immune processes in CIA." (PMID 35083342, 2022). "Moreover, in an adjuvant-induced arthritis model, astrocytes expressing GFAP were increased in number and immunostaining intensity in the spinal cord and were associated with increased levels of cytokines such as IL-1β, IL-6, and TNF." (PMID 36387416, 2022). "However, others cytokines were similarly expressed in both groups; and arthritis-induced bone loss was not altered by the lower level of TNFA, as TNF plays a major role in MMP production and osteoclastogenesis stimulation." (PMID 35558888, 2022). "As penfluridol could inhibit TNFα-induced NF-κB activity and was effective to alleviate the severity of TNFα and TNFα-stimulated NF-κB activation-driven arthritis, we assessed the treatment efficacy of penfluridol in another TNFα-dominant autoimmune disease, IBD." (PMID 35045889, 2022).
Arthritis (continued). "Therefore, our findings may shed light on the pathogenesis of ICI-related arthritis and pneumonitis, and TNF-α secreting T cells may be therapeutic targets for intervention of ICI-related arthritis and pneumonitis." (PMID 36016934, 2022). "The in vivo results showed that corilagin significantly reduced paw swelling and arthritis score and inhibited joint erosion and the infiltration of inflammatory cells; pro-inflammatory cytokines were also inhibited at the serum level (IL-6, TNF-α, IL-1β, and IL-17)." (PMID 36364420, 2022). "Thus, TNF-α alone overexpression is sufficient to establish arthritis model in animals." (PMID 36288143, 2022). "Overall, arthritis was significantly more common (according to logistic regression analysis) in patients requiring biological therapy, and patients with arthritis detected at the onset of their CD (n = 18) received more aggressive treatment, including the TNF-inhibitor biologic infliximab." (PMID 35093127, 2022). "During TNF-mediated arthritis, the S4a(Prg4high/Tspan15+) LSFs preserve some of their homeostatic marker gene identity, but also show an expansion in the diversity of their transcriptome, indicating that their reparative functions might be affected after disease onset." (PMID 35879783, 2022). "Therefore, it necessitates reduction of TNF-α to avoid cartilage and bone damage in arthritis." (PMID 34712426, 2021). "Based on these findings, the aim of this study was to elucidate whether FLS-derived myostatin is involved in the recruitment of immune cells to the inflamed tissues thereby contributing to the persistence of joint inflammation in a chronic TNF-a-mediated arthritis mouse model." (PMID 34239010, 2021). "Interestingly, this combination therapy significantly ameliorated both clinical and histopathological signs of arthritis, thus indicating a potential for a broader range of kinase inhibitors to synergize with anti-TNF agents to efficiently treat arthritis pathology." (PMID 33892739, 2021). "In inflammatory arthritis, further signaling pathways may be favorably affected by vitamin K. Thus, NFκB signaling, a target of tumor necrosis factor α (TNFα) and other pro-inflammatory cytokines are elevated in arthritis FLSCs and a well-known driver of synovial hyperplasia." (PMID 34502245, 2021). "Furthermore, Haidalimumab could effectively neutralize rhTNFα toxicity in a C57BL/6 mouse model, and displayed significant therapeutic effect in a TNF-Tg mouse arthritis model." (PMID 34886761, 2021). "Indeed, a study in a human TNF transgenic arthritis model suggested that TNF-induced bone and cartilage damage may be mediated by IL-1." (PMID 33605409, 2021). "In addition, TNF-α-expressing transgenic mice can spontaneously develop arthritis." (PMID 34638736, 2021). "In addition, SIN downregulates iNOS, COX-2, NO, PGE2, TNF-α, and IL-6 induced by IL-1β, suggesting that it protects chondrocytes by promoting autophagy and preventing cartilage degradation, thereby reducing the clinical symptoms of arthritis." (PMID 35173609, 2021). "The progression of arthritis disease is regulated by several microRNAs (miRNAs), including miR-92a, miR-129-3p, miR-141-3p and miR-199a-5p, while the proinflammatory mediators IL-1β, IL-6, TNF-α and matrix metalloproteinases (MMPs) account for histological changes that occur with arthritis." (PMID 34198264, 2021). "Similarly, bone phenotype spontaneous mutation 1 (BPSM1) mice that have increased TNF expression due to a spontaneous insertion of a small interspersed element (SINE) in the 3’ untranslated region of Tnf, develop severe, progressive arthritis and valvular endocarditis with aortic aneurysm." (PMID 32671059, 2020). "In the DBA/1 mouse model of collagen-induced arthritis, adiponectin treatment significantly alleviated the severity of arthritis together with a decrease in the expression of pro-inflammatory cytokines such as TNF-α and IL-1, and the reduction of metalloproteinase (MMP)-3 in synovial tissues." (PMID 32362840, 2020).
Arthritis (continued). "Thus, A20 protects cells from TNF-induced and NF-κB-mediated inflammation and arthritis." (PMID 32958016, 2020). "Taken together, our study shows that infliximab treatment not only affect systemic inflammation but also associate with changes in inflammatory markers in the CSF of arthritis patients, which may help explain the ability ofinfliximab and other TNF-blocking agents to relieve CNS-related symptoms." (PMID 30770760, 2019). "Hence, in an TNF-overexpression model of arthritis (TNFΔARE mice), which resembles an effector model of arthritis with features partly resembling human spondyloarthritis (SpA), mice that had been voluntarily running developed significantly exacerbated disease)." (PMID 30397205, 2018). "Finally, a recombinant vaccine mTNF-PADRE was obtained which can adjuvant-freely induce a high titer mouse TNF-α-specific neutralizing antibodies which can potently attenuate LPS induced endotoxic shock, TNF-α induced cachexia, and collagen-II-induced arthritis (CIA) in mice." (PMID 29850502, 2018). "Surprisingly, CD-1 mice with Smad7 deficiency developed severe arthritis including severe joint swelling, synovial hyperplasia, cartilage damage, massive infiltration of CD3+ T cells and F4/80+ macrophages, and upregulation of proinflammatory cytokines IL-1β, TNFα, and MCP-1." (PMID 30450102, 2018). "Whereas TNF and IL-1β share some pro-inflammatory activity in arthritis, the reduction in these cytokines after 30 days of Col V supplementation suggests that this might be an adjunct to therapy for arthritis." (PMID 30059520, 2018). "Thus, we believe that IL-7, such as TNF-α, IL-6, and IL-1, is a potent factor that can itself induce osteoclasts, suggesting the potential of IL-7 as the “best” therapeutic target for alleviating arthritis by suppressing both inflammation and bone erosion." (PMID 29104576, 2017). "Therefore, our findings suggest that anti-TNFα could have an even earlier effect in preventing and restoring arthritis-induced bone destruction if patients respond to the therapy." (PMID 28978352, 2017). "Thus, TNFKi was effective in protecting against TNF-mediated arthritis in mice." (PMID 29184553, 2017). "However, similar improvement rates upon anti-TNF-α therapy in the different localizations may indirectly support appropriate DIP arthritis assessment being truly inflammatory." (PMID 28432523, 2017). "However, an alternative explanation could be that anti-TNFα ameliorates arthritis in responder patients by binding to autoreactive effector T cells that express membrane TNFα and thereby ameliorate their pro-inflammatory effects." (PMID 28488248, 2017). "Since the suppression of TNF-α production and augmentation of IL-10 expression are thought to be a favorable approach for treating RA, we speculated that the administration of TJ-20 could be an ideal therapy for arthritis." (PMID 28555160, 2017). "Immunosuppressive therapies frequently used in the treatment of RA (especially TNF-α inhibitors) have been known to induce reactivation of latent T. gondii infection in arthritis patients, and may increase their propensity to acquire new opportunistic infections such as T. gondii or tuberculosis." (PMID 29065914, 2017). "Further, we have shown that TNF-α-induced lung inflammation is not sufficient to cause murine arthritis, suggesting that lung and joint inflammation are two separate outcomes of a single underlying pathologic process instead of lung inflammation driving murine inflammatory arthritis." (PMID 27450561, 2016). "The fact that M-CSF plays a central role in TNF-induced osteoclastogenesis is confirmed by the capacity of an antibody directed against the M-CSF receptor, c-Fms, to completely arrest pathological osteoclastogenesis and bone resorption, inflammation in a serum-transfer arthritis model." (PMID 26634933, 2016). "People with more severe arthritis could be more likely to receive TNF inhibitor." (PMID 27630714, 2016).
Arthritis (continued). "The absence of specific MHC variants may explain the absence of autoantibodies that uniquely target citrullinated antigens in mice that overexpress TNF-α as well as possibly the inability for TNF-α-induced lung inflammation to independently drive murine arthritis." (PMID 27450561, 2016). "In the second trial, also in a murine model, in which over-expression of the modified human TNF-α gene to prevent degradation of its mRNA is associated with the development of RA 4–6 months after the birth of the animals, the administration of anti-TNF-α demonstrated the prevention of arthritis." (PMID 24980068, 2015). "In addition, Conti and colleagues reported that imaging with anti-TNF-α in patients with active arthritis just before treatment with infliximab could predict the efficacy of the anti-TNF-α therapy." (PMID 25099015, 2014). "Using mice with tumor necrosis factor α (TNFα)–induced arthritis in which fak could be inducibly deleted, invasion and migration by FAK-deficient murine arthritic synovial fibroblasts were determined and arthritis was clinically and pathologically scored in FAK-deficient mice." (PMID 25280866, 2014). "As the combination of TNF blockade and recombinant IL-10 had previously exhibited encouraging results in the collagen-induced arthritis model, we became interested in studying whether a combination with F8-IL10 would also exhibit a potent inhibition of disease progression." (PMID 24289726, 2013). "Another member of the tenascin family, Tenascin C (Tnc), was recently shown to be an endogenous activator of TLR4, an inducer of IL-6 and TNFα, and was required for joint damage in arthritic mice, suggesting that Tnn could have a function similar to Tnc in arthritis." (PMID 23249408, 2012). "Therefore, similar to the positive drug indomethacin, EMI may be served as an antigouty arthritis agent mediated by inhibition of cytokines expression such as TNF-α and IL-1β." (PMID 23304232, 2012). "Therefore, we sought to investigate whether this mechanism also holds for arthritis models that are known to be partly TNF-dependent, including SCW and CIA." (PMID 20370892, 2010). "We hypothesized that RANKL inhibition would prevent local and systemic bone loss without inhibiting systemic markers and mediators of inflammation in both AIA and CIA rats, while inhibition of IL-1 or TNFα would suppress systemic levels of proinflammatory cytokines in these two arthritis models." (PMID 20003323, 2009). "Therefore, intra-articular blockade of TNF-α could be a possible therapy for patients with arthritis in the TMJ." (PMID 19200377, 2009). "Here we present a multi-step proteomics approach using arthritis antigen arrays, a multiplex cytokine assay, and conventional ELISA, with the objective to identify a biomarker signature in three ethnically diverse cohorts of RA patients treated with the anti-TNF therapy etanercept." (PMID 19460157, 2009). "Whether HMGB1-induced arthritis is mediated via the TNFα pathway, however, is unknown." (PMID 18582368, 2008). "However, this negative correlation suggests but does not establish a causal relationship between endogenous TNFα and protection against arthritis." (PMID 18380898, 2008). "Considering the critical role of TNFα in the initiation and propagation of arthritis, we had anticipated that the level of TNFα might be high in the early phases of AA (for example, Inc, Ons, and/or Pk), but relatively much lower in the later phases (for example, Rec) of the disease." (PMID 18380898, 2008). "However, leukocyte infiltration at 24 hours and beyond and the loss of proteoglycan in S. aureus-induced arthritis were not affected by anti-TNF-α mAb, IL-1ra, or their combination." (PMID 17129374, 2006).